LINC02151 (long independently transcribed non-coding RNA 2151)
Synonyms: uc.332; TCONS_00019174
Gene: Long non-coding RNA gene on chromosome 11 (116,320,214 to 116,500,654, reverse strand). Ensembl gene ENSG00000236437.
Gene Ontology:
Biological process: RNA processing
Cellular component: nucleolus